PAX5 (paired box 5)
Diseases named in the same sentence as PAX5 in open-access papers (continued):
Sharing a sentence is not in itself a finding about the gene and the disease.
small cell lung carcinoma (4 papers, 2014 to 2022). Small cell lung cancer (SCLC) is a highly aggressive malignant neoplasm, accounting for 10-15% of lung cancer cases, characterized byrapid growth, and early metastasis. "Subsequent studies from our lab also revealed that PAX5 transcription factor is preferentially expressed in small cell lung cancer (SCLC) and promotes MET transcription." (PMID 24628993, 2014). "Notably, PAX5 facilitates the proliferation of small-cell lung cancer cells by binding to the c-Met promoter sequence." (PMID 36064939, 2022).
bladder cancer (3 papers, 2022 to 2023). "Mechanistically, this latter study demonstrates that the PAX5 transcription factor transactivates Prostaglandin-Endoperoxide Synthase-2 gene transcription, which promotes bladder cancer pathogenic features." (PMID 36077495, 2022). "The knockdown of PAX5 improved cisplatin sensitivity of bladder cancer cells, whereas the overexpression of PAX5 increased cisplatin resistance." (PMID 37627900, 2023). "Nuclear PAX5 protein was only detected in 0.2–10% of bladder cancer cases, thus suggesting that PAX5 may only play a minor functional role in bladder cancer." (PMID 37627900, 2023). "However, PAX5 mRNA expression has been detected in 79% of bladder cancer tissues and cell lines (RT112, HT-1376 and MGH-U1)." (PMID 37627900, 2023). "PAX5 was significantly increased in cisplatin-resistant bladder cancer tissues and cell lines." (PMID 37627900, 2023). "Another interaction PAX5 with miR-5699 was found in BLCA (bladder cancer) and OV (ovarian)." (PMID 35260634, 2022). "PAX5 mRNA expression was detected in 83.3% of bladder cancer patients, whereas negative PAX5 expression was detected in the control group." (PMID 37627900, 2023). "PAX5 protein expression is not frequently detected in bladder cancer." (PMID 37627900, 2023).
cervical cancer (3 papers, 2019 to 2021). A primary or metastatic malignant neoplasm involving the cervix. "The mean levels of CNOT7, PAX5, and SPDEF are slightly elevated in CESC samples compared with those in healthy tissue, though not significantly, while the level of TGM2 is significantly downregulated in cervical cancer." (PMID 30918060, 2019).
chronic myeloid leukemia (3 papers, 2013 to 2022). "PAX5, CD19 and CD79b are all absent in K562 (a non-B Chronic Myelogenous Leukemia cell line)." (PMID 33452395, 2021).
esophageal cancer (3 papers, 2021 to 2024). A primary or metastatic malignant neoplasm involving the esophagus. "Altogether, the data suggest that PAX5 gene methylation might predict cisplatin resistance and poor survival outcomes and may serve as a valuable diagnostic tool for cancer therapy of esophageal cancers." (PMID 38256203, 2024). "In esophageal cancer cell lines, it was shown that PAX5 knockdown resulted in resistance to cisplatin, and the presence of methylation marks in the PAX5 gene may be a diagnostic marker of cisplatin resistance, as well as of a poor survival prognosis." (PMID 39062899, 2024). "In models of esophageal cancer cell lines, PAX5 knockdown resulted in cisplatin resistance, supporting the notion of PAX5 as a contributor to cisplatin resistance." (PMID 38256203, 2024).
glioma (3 papers, 2021 to 2023). A benign or malignant brain and spinal cord tumor that arises from glial cells (astrocytes, oligodendrocytes, ependymal cells). "TFBS identified within open chromatin regions in cultured glioma cells contained numerous motifs for the AP2D, PAX5, and ZFX binding proteins, among many others." (PMID 36850002, 2023). "Transcription factor PAX5 (Paired Box Gene 5) promotes gliomagenesis and cooperates with factors such as MYC, FOS, or JUN, which are highly expressed in gliomas." (PMID 36850002, 2023). "We detected TF binding sites for E2F1, HMX1, PAX5, REST and ZBTB6 in the promoters of DEGs present within the top six ‘glioma TADs’." (PMID 34341417, 2021).
Granuloma (3 papers, 2017 to 2025). A compact, organized collection of mature mononuclear phagocytes, which may be but is not necessarily accompanied by accessory features such as necrosis. "In both HIV-uninfected and coinfected tissue, we noted the presence of Pax5-positive B cells diffusely distributed within the tissues, but not within the center of granulomas." (PMID 28955338, 2017).
lupus (3 papers, 2018 to 2025). "The reciprocal regulation between METTL3 and PAX5 highlights a critical mechanism underlying B-cell activation and persistence in autoimmune conditions like lupus." (PMID 40506739, 2025). "mTORC1 is found to be highly activated and AICDA, its transcriptional activator PAX5, and BCL6 are overexpressed in a population of atypical memory B cells in patients with active lupus." (PMID 33557396, 2021).
MALT lymphoma (3 papers, 2016 to 2023). An indolent, extranodal type of non-Hodgkin lymphoma composed of small B-lymphocytes (centrocyte-like cells). "In this study, tumor cells from thymic MALT lymphoma expressed B-cell markers (CD20 and PAX5), which demonstrates that MALT lymphomas originate in the marginal zone (MZ) of B cells." (PMID 35911381, 2022).
marginal zone lymphoma (3 papers, 2013 to 2023). A usually indolent mature B-cell lymphoma, arising from the marginal zone of lymphoid tissues. "Immunohistochemistry in marginal-zone lymphomas and DLBCL confirmed a B-cell origin, given the strong expression of PAX5 and the lack of CD3 immunoreactivity." (PMID 37104402, 2023).
small cell carcinoma (3 papers, 2014 to 2023). A neuroendocrine carcinoma composed of small malignant cells which are often said to resemble "oat cells" under the microscope. "Careful interpretation of PAX5 without confirmation of a hematolymphoid origin (CD45, CD43) should be kept in mind since up to 30% of small cell carcinomas can be positive for PAX5, and some cases of small cell carcinoma may be negative or only patchy positive for keratins and synaptophysin." (PMID 37958219, 2023). "Biopsy specimen stained positive for CK, CD56, NSE, BcL2, Synaptophysin, PAX-5, and TTF-1, but negative for Chromogranin, CD57, and NFP; consistent with small cell carcinoma." (PMID 30428872, 2018).
viral infection (3 papers, 2014 to 2021). "Therefore, we need to consider the regulation of CD81 transcription by transcription factors other than Pax5 under special conditions, such as cytokine stimuli, stress responses, viral infection, and B-cell developmental stages." (PMID 34824296, 2021). "Other B lymphocyte markers such as Blimp1, Pax5, or markers related with antigen presentation cells like MHC-II or Lamp3 showed no significant regulation due to viral infection at the time periods studied." (PMID 25338079, 2014).
alveolar rhabdomyosarcoma (2 papers, 2021 to 2023). A rapidly growing malignant mesenchymal neoplasm. "What should be considered is that PAX5 can be expressed not only in B lymphocytes but also in some neuroendocrine carcinomas and rhabdomyosarcomas." (PMID 37182167, 2023). "In cell cycle analysis, rhabdomyosarcoma cells with high expression of PAX5 and LTB were significantly located in the G2M and S phases." (PMID 33397394, 2021). "Additionally, PAX5, LTB and CD44 (markers of stem cells) were significantly colocalized in the scRNA-seq data of the human alveolar rhabdomyosarcoma cell line Rh41." (PMID 33397394, 2021).
autism (2 papers, 2024 to 2025). Persistent deficits in social interaction and communication and interaction as well as a markedly restricted repertoire of activity and interest as well as repetitive patterns of behavior. "PAX5, which represents an autism risk gene involved in gene expression regulation, peaked during the middle phase of this lineage within neuroblast cells of the fetal first trimester." (PMID 39363111, 2024). "For example, we identified transcripts of candidate genes for autism not expressed in the brain (Pax5) or specifically absent in brainstem (Arx, Foxg2) or striatum (Ebf3)." (PMID 39920851, 2025).
autism spectrum disorder (2 papers, 2022 to 2023). A spectrum of developmental disorders that includes autism, and Asperger syndrome. "A mouse model carrying biallelic Pax5 mutations identified in a patient with hypogammaglobulinemia and autism spectrum disorder shows a B cell developmental arrest and autistic-like behavior caused by abnormal development of the cerebellum and loss of ventral midbrain GABAergic neurons." (PMID 35947077, 2022). "Recently, germline PAX5 alterations have been described in individuals with autism spectrum disorder." (PMID 37543654, 2023). "Our patient has not been diagnosed with autism spectrum disorder, nor was this reported in the families with a germline PAX5 missense variant." (PMID 37543654, 2023).
B-cell neoplasm (2 papers, 2009 to 2021). A group of heterogeneous lymphoid tumors generally expressing one or more B-cell antigens or representing malignant transformations of B-lymphocytes. "Like other mature B cell neoplasms, FL expresses pan-B cell antigens (CD19, CD22, CD79a and PAX5), and is also by definition positive for germinal center markers, such as BCL6, HGAL and LMO2." (PMID 34898578, 2021).
carcinoid (2 papers, 2023 to 2024). "Interestingly, in neuroendocrine lung cancer, heterogeneous expression of Pax5 has been reported with the highest in the small-cell (SCLC) subtype, followed by large cell and carcinoid." (PMID 39183332, 2024).
COVID-19 (2 papers, 2021). A disease caused by infection with severe acute respiratory syndrome coronavirus 2. "High PGE2 in COVID-19 serum impairs the B-cell mediated immune response at least in part by reducing PAX5." (PMID 34347801, 2021). "Serum from COVID-19 patients with elevated PGE2 levels reduced the expression of PAX5 in SUP-B15 cells compared with serum from healthy controls." (PMID 34347801, 2021). "Moreover, PGE2 levels in serum of COVID-19 patients lowers the expression of PAX5 in human pre-B-cell lines." (PMID 34347801, 2021). "In addition to already known effects of PGE2 on immune cells, we discovered a novel mechanism by which PGE2 in serum from COVID-19 patients specifically impacts on pre-B-cells since PGE2 in the sera of COVID-19 patients reduces the expression of PAX5 in human pre-B-cells via its EP4 receptor." (PMID 34347801, 2021). "Here, we observed that the addition of PGE2 (10 μM, i.e. 3525 pg/ml), in the range measured in COVID-19 patients’ sera (1300 to >20.000 pg/ml), to two human B-cell precursor lines, 697 and SUP-B15, significantly reduced PAX5 mRNA expression." (PMID 34347801, 2021). "In all, 8 out of 107 HSC/MPP cells in HC and 2 out of 77 HSC/MPP cells in COVID-19 patients with mild disease expressed ID3, but not in severe cases, although PAX5 and EBF1 were not identified." (PMID 34349096, 2021).
depression (2 papers, 2021 to 2024). "PAX5 was previously found to be related to PTSD and depression." (PMID 39060246, 2024).
Down syndrome (2 papers, 2018 to 2025). "Many genetic factors have been shown to be associated with an increased risk of ALL, including Down syndrome, germline mutations in PAX5 and ETV6 and polymorphic variants in specific genes." (PMID 40122536, 2025). "Pre-B ALL occurs more commonly in Down syndrome individuals and is felt to be biologically distinct from disease occurring in non-Down syndrome patients; nevertheless, inactivating mutations of PAX5 are detected at similar frequency in Down syndrome-associated pre-B ALL." (PMID 30216339, 2018).
histiocytic sarcoma (2 papers, 2023 to 2026). An aggressive malignant neoplasm with a poor response to therapy, usually presenting as stage III/IV disease. "In conclusion, we report a case of PAX5 P80R-mutated B-ALL followed by histiocytic sarcoma in which combined NGS-based IG clonality and mutational analysis elucidated the clonal relationship and evolution." (PMID 36241730, 2023). "In this pediatric PAX5-P80R-mutated cohort, no subsequent malignancies, like histiocytic sarcoma, were described during follow-up." (PMID 36241730, 2023).
hypogammaglobulinemia (2 papers, 2022 to 2023). "A patient-specific Pax5 mutant mouse revealed an early B cell developmental block and impaired immune responses as the cause of hypogammaglobulinemia." (PMID 35947077, 2022). "By identifying a patient with biallelic PAX5 mutations, we now demonstrate that PAX5 deficiency can also cause neurodevelopmental abnormalities including ASD in addition to hypogammaglobulinemia." (PMID 35947077, 2022). "Thus, human PAX5 deficiency blocks B cell development resulting in B cell cytopenia, hypogammaglobulinemia, and impaired Ab responses." (PMID 37273190, 2023). "Hence, biallelic PAX5 mutations cause a novel form of hypogammaglobulinemia." (PMID 35947077, 2022). "Recently, individuals with B lymphopenia, agammaglobulinemia, and recurrent sinopulmonary infections due to mutations in TCF3, SPI1, PAX5, IKZF1, or IKZF3 have been reported." (PMID 37273190, 2023). "Here, we report a patient with hypogammaglobulinemia and ASD who carries biallelic mutations in the transcription factor PAX5." (PMID 35947077, 2022).
invasive ductal adenocarcinoma (2 papers, 2017 to 2025). "They observed frequent promoter hypermethylation of BRCA2, CDH13, MSH6, PAX5, PAX6, and WT1 genes in both DCIS and adjacent invasive ductal adenocarcinoma lesions." (PMID 40131297, 2025).
lung adenocarcinoma (2 papers, 2016 to 2019). A carcinoma that arises from the lung and is characterized by the presence of malignant glandular epithelial cells. "In addition, we found that methylation of PAX5 promoter was correlated with lung adenocarcinoma." (PMID 26843424, 2016). "Stable transfection was performed in two lung adenocarcinoma cell lines A549 and H1975 that had no intrinsic PAX5 expression and re‐expression of PAX5 was confirmed by semi‐quantitative PCR and real‐time PCR." (PMID 26843424, 2016). "Data from Oncomine database showed that PAX5 is down‐regulated significantly in lung adenocarcinoma but not squamous carcinoma." (PMID 26843424, 2016). "However, it is shown recently that PAX5 was down-regulated significantly in lung adenocarcinoma but not squamous carcinoma." (PMID 31877723, 2019).
lymphopenia (2 papers, 2023 to 2025). Reduction in the number of lymphocytes. "SFTSV infection can damage T lymphocytes through the Fas/FasL‐mediated apoptosis pathway, and the SFTSV also targets immature B cells that express PAX5, possibly leading to severe lymphopenia." (PMID 40988472, 2025).
Merkel cell carcinoma (2 papers, 2014 to 2022). "For example, cytokeratin AE1/AE3, CK20, and PAX5 immunostains were ordered on aspirated material from parotid gland of a patient previously diagnosed for Merkel cell carcinoma to confirm a metastatic process or TTF‐1 and Napsin‐A were reviewed to rule out a metastatic lung adenocarcinoma." (PMID 35092649, 2022).
metastatic cancer (2 papers, 2023 to 2024). A carcinoma which has spread from the original site of growth to another anatomic site. "By re-analyzing these RNA-seq expression data, we found that Pax5 expression is higher in metastatic cancer with neuroendocrine differentiation." (PMID 38168280, 2023).
neuroendocrine carcinoma (2 papers, 2014 to 2023). A malignant neuroendocrine neoplasm composed of cells containing secretory granules that stain positive for NSE and chromogranin. "In this study, one lymph node biopsy demonstrated only PAX5, which was weakly positive in the T/B lineage markers, but showed CKpan, Syn and CD56 positivity in subsequent immunostains; a neuroendocrine carcinoma was subsequently diagnosed." (PMID 37182167, 2023).
Osteopenia (2 papers, 2021 to 2022). Osteopenia is a term to define bone density that is not normal but also not as low as osteoporosis. "Furthermore, Pax5−/− mice exhibit severe osteopenia with a loss of bone mass of more than 60% and an increase in the OC number." (PMID 33672551, 2021). "Blocking B cell development at an early stage with Pax5 deletion leads to an early death with severe osteopenia due to an increase in the number of osteoclasts." (PMID 36189270, 2022). "Pax5−/− mice exhibit severe osteopenia with an increase in the OC number and acceleration of bone loss." (PMID 33672551, 2021).
plasma cell disorder (2 papers, 2022 to 2025). "Biopsy revealed a kappa-restricted plasma cell neoplasm with strong CD138, BCL2, CD20, and PAX5 expression and absence of MYD88 L265P mutation via immunohistochemistry." (PMID 41346800, 2025).
prostate adenocarcinoma (2 papers, 2023 to 2024). "Pax5 expression is highly selective for NE-like cancer but not for prostate adenocarcinoma." (PMID 38168280, 2023).
retinoblastoma (2 papers, 2022 to 2025). A malignant tumor that originates in the nuclear layer of the retina. "The upregulated Pax5 further inhibited the proliferation, migration, and invasion of retinoblastoma cells, and promoted cell apoptosis." (PMID 41150792, 2025). "It is known that Pax5 inhibits the growth of retinoblastoma by inhibiting the activity of the Notch1 signaling pathway." (PMID 41150792, 2025). "This was a result of the higher methylation level of the Pax5 gene in retinoblastoma cells, rather than normal retinal epithelial cells." (PMID 41150792, 2025).
sarcoma (2 papers, 2015 to 2021). A usually aggressive malignant neoplasm of the soft tissue or bone. "PAX5 and LTB proteins were shown to be significantly downregulated in the tumour cells of primary sarcomas with metastasis based on IHC." (PMID 33397394, 2021). "CD45, CD20, CD79a, and PAX5 should be positive in DLBCL as in our case, while other markers for sarcoma including smooth muscle actin, muscle specific actin, and desmin should be negative." (PMID 25984371, 2015). "However, PAX5 and LTB proteins were shown to be significantly downregulated in the tumour cells of primary sarcomas with metastasis." (PMID 33397394, 2021). "The results of the Mann–Whitney U test suggested that PAX5 (P < 0.001) and LTB (P < 0.001) were all highly expressed in well-differentiated primary sarcomas and primary sarcomas without metastasis." (PMID 33397394, 2021).
Type 2 diabetes (2 papers, 2023 to 2024). "PAX5, functioning as a classical transcription factor, can regulate the expression of many genes, such as MYC, WAPL, and several type 2 diabetes-related genes, including SFRP1 and SYT12." (PMID 38926764, 2024).
acute promyelocytic leukemia (1 paper, 2023). An aggressive form of acute myeloid leukemia (AML), characterized by arrest of leukocyte differentiation at the promyelocyte stage, due to a specific chromosomal translocation t(15;17) in myeloid cells. "Although a direct role for RARA in PAX5-altered B-ALL has not been established, previous work has identified PAX5 as a target gene of the PLZF-RARA fusion protein in acute promyelocytic leukemia." (PMID 38116118, 2023).
atherosclerosis (1 paper, 2022). A disease characterized by the build-up of fatty material and calcium deposition in the arterial wall resulting in partial or complete occlusion of the arterial lumen. "In agreement with this, elimination of GC B cells achieved upon deletion of the key B cell transcription factor Pax5 in AID-expressing B cells, reduced atherosclerosis." (PMID 35497984, 2022). "In addition, genetic deletion of the B cell transcription factor Pax5 in CD23-expressing cells (primarily mature B2 cells), or treatment with an agonistic antibody specific for B- and T-lymphocyte attenuator that reduced mature B-2 cells, also resulted in decreased atherosclerosis." (PMID 35497984, 2022).